CXCL1 (C-X-C motif chemokine ligand 1)
Diseases named in the same sentence as CXCL1 in open-access papers (continued):
Sharing a sentence is not in itself a finding about the gene and the disease.
ulcerative colitis (16 papers, 2008 to 2025). An inflammatory bowel disease involving the mucosal surface of the large intestine and rectum. "Compared with traditional biomarkers such as fecal calprotectin, the expression level of CXCL1 in ulcerative colitis (UC) is closely related to the infiltration of various immune cells, including neutrophils, M1 macrophages, and activated dendritic cells." (PMID 40630894, 2025). "Three of four hub genes identified as NF-κB-regulated in active ulcerative colitis were also regulated in PC-3 MCS in our study (CXCL1, MMP1, and MMP10)." (PMID 40001606, 2025). "Pretreatment with D-e-MAPP in Slc39a8-IEC KO mice also reduced the expression of inflammation markers, including Cxcl1 and Tnfa, which are hallmarks of ulcerative colitis." (PMID 38839750, 2024). "Serum levels of CXCL1 are elevated in patients with Crohn’s disease and ulcerative colitis, where levels of CXCL1 are higher in ulcerative colitis than in Crohn’s disease." (PMID 35806156, 2022). "UroA/UAS03 treatment also reduced neutrophil infiltration as evident from myeloperoxidase (MPO) activity as well as serum inflammatory markers such as IL-6, TNF-α, CXCL1, and IL-1β that are hallmarks of ulcerative colitis." (PMID 30626868, 2019). "Analyses of changes in gene expression indicate that CXCL1 is a hub gene in ulcerative colitis." (PMID 35806156, 2022). "Elevated CXCL1 expression has also been found in mucosal biopsies in patients with Crohn’s disease and ulcerative colitis, again with a higher expression of CXCL1 in ulcerative colitis than in Crohn’s disease." (PMID 35806156, 2022). "Moreover, the expressions of CXCL1 and IL-8 are reciprocally related; according to the data observed in the spontaneous equine acute models in the present study, both also increase in human patients during ulcerative colitis, a chronic inflammatory disease." (PMID 33330716, 2020). "Previous studies have demonstrated that the expression of CCL9, CXCL1, and CXCL2 is significantly increased in the colonic epithelial cells of experimental colitis mice and ulcerative colitis (UC) patients." (PMID 39896755, 2025). "In conclusion, core genes (CXCL1 and BCL6) are effectiveness biomarkers for evaluating the progression from ulcerative colitis to cancer." (PMID 39582536, 2024). "Additionally, in a study on perfusates from patients with demonstrated elevated levels of CXCL1, the concentration of CXCL1 was 3 times higher than CXCL8/IL-8, which indicates that in ulcerative colitis, CXCL1 has a major function among CXCR2 ligands." (PMID 35806156, 2022). "Additionally, mucosal biopsies from patients with ulcerative colitis show higher expression of another CXCR2 ligand: CXCL8/IL-8, which indicates that CXCL1 does not act alone but rather with other CXCR2 ligands." (PMID 35806156, 2022).
gout (15 papers, 2016 to 2025). A condition characterized by painful swelling of the joints, which is caused by deposition of urate crystals. "Additionally, PA strongly eliminated inflammation and gout risk by downregulating macrophage and neutrophil invasion, as well as CXCL1 and TLR2 expressions." (PMID 39060811, 2024). "CXCL1 orchestrates neutrophil-dominated inflammation in gout through feedforward loops with NLRP3 inflammasome activation." (PMID 40388724, 2025). "Since IL-1β and IL6 have been linked to gout in numerous studies, our main focus was on the connection between CXCL8, CXCL1, and CXCL2 and acute gouty arthritis." (PMID 38686389, 2024). "While the mean reduction by anti–IL-1β was comparatively small, it is interesting to note that a small subset of RA and gout synovial fluids showed stronger decreases of CXCL1/5 secretion upon anti–IL-1β treatment." (PMID 35801586, 2022). "Synovial fluids from patients with RA and gout elicit CXCL1 and CXCL5 from synovial fibroblasts via IRAK1." (PMID 35801586, 2022). "A similar observation was previously made using an NLRP3 inhibitor in a gout model, which also suppressed IL-6 and CXCL1 in synovial tissue after MSU crystal injection." (PMID 36225929, 2022). "The analysis results indicate that FGF-21, MMP-1, G-CSF, and IFN-γ are involved in the pathogenesis of gout, and gout may influence the expression of CXCL1, IL-1Ra, and TNF-α." (PMID 40388724, 2025). "The ability of the ceRNA network to predict miRNAs and lncRNAs upstream of CXCL8, CXCL1, CXCL2, IL-1β, and IL6 may lead to the use of a novel diagnostic and prognostic marker for gout." (PMID 38686389, 2024). "Indeed, synovial fluid from multiple patients with RA or gout elicited CXCL1 and CXCL5 release from murine synovial fibroblasts." (PMID 35801586, 2022). "Furthermore, the reverse MR analysis suggests that elevated levels of CXCL1, IL-1Ra, and TNF-α may be a consequence of gout, with these associations remaining robust after sensitivity analysis." (PMID 40388724, 2025). "Compared with WT mice, St2-/- mice showed significantly reduced expression of IL-1β, IL-6, IL-13, CCL11, G-CSF, CXCL1, CCL2 and CCL3 proteins in ankle tissues, suggesting St2-/- mice showed generally attenuated inflammatory response during gout." (PMID 33204337, 2020). "A study on gout shows that colchicine treatment significantly reduced MSU crystal-induced secretion of inflammatory cytokines (IL-1β and CXCL1) from macrophages and promoted macrophage differentiation into the anti-inflammatory M2 phenotype." (PMID 32733639, 2020). "Specifically, we identified multiple CIPs, including FGF21, MMP-1, G-CSF, IFN-γ, CXCL1, IL-1Ra, and TNF-α, which may serve as potential molecular therapeutic targets for gout." (PMID 40388724, 2025). "Our findings could lead to the development of new approaches for the treatment of gout; however, the precise regulatory mechanisms of CXCL8, CXCL1, and CXCL2 in gout remain unclear." (PMID 38686389, 2024). "In summary, CXCL8, CXCL1, and CXCL2 may be gout biomarkers, and this research may lead to novel approaches for the clinical management of individuals with gouty arthritis." (PMID 38686389, 2024). "We reason here that IL-33, after being released from macrophages, may act in an autocrine manner to induce CXCL1, CCL3 and IL-1β production via ST2 in macrophages during gout." (PMID 33204337, 2020). "Indeed, increased levels of CXCL8 (IL-8), CXCL1 (KC) and CXCL10 (IP-10) have been detected in synovial fluid in patients with gouty arthritis." (PMID 27863506, 2016).
liver cancer (15 papers, 2016 to 2025). An epithelial or non-epithelial malignant neoplasm that arises from the liver. "We restored Cxcl1 and Il8 to attempt to rescue the loss of Phgdh/cMyc axis‐regulated immune functions in liver cancer progression." (PMID 37078828, 2023). "CXCL1 is important in the emergence of liver cancer, as demonstrated by studies on genetic polymorphisms in patients with liver cirrhosis and HCC." (PMID 37408240, 2023). "Higher CXCL1 expression in the tumor is associated with a worse prognosis for liver cancer patients, including HCC." (PMID 37408240, 2023). "Decreased SLC7A2 level induced the expression of multiple liver cancer-related genes, CXCL1 was strongly induced by deficient SLC7A2 expression." (PMID 34108444, 2021). "Additionally, a recent study found that upregulation of CXCL1 gene expression significantly recruits tumor-associated neutrophils, leading to NETs formation and promoting liver cancer metastasis." (PMID 40309357, 2025). "Then, CXCL1 and IL8 promote neutrophil recruitment and enhance tumor‐associated macrophage (TAM) filtration in the liver, thereby advancing liver cancer." (PMID 37078828, 2023). "To verify the role of PHGDH/cMyc axis‐regulated Cxcl1/Il8 expression in liver cancer progression, we delivered AAV carrying Phgdh‐WT or Phgdh‐dACT under the thyroid hormone binding globulin promoter into PhgdhLKO adult mice." (PMID 37078828, 2023). "In patients with liver cancer, blood CXCL1 levels are elevated compared to healthy individuals and those with liver cirrhosis." (PMID 37408240, 2023). "It is markedly down-regulated in AH and liver cancer, whereas hepatic production and serum CXCL1 and CXCL8 are highly elevated and correlated AH severity in humans." (PMID 39619227, 2023). "The serum mRNA and protein expression levels of CXCL1 in primary liver cancer patients were detected by qRT‐PCR and western blot analysis, respectively." (PMID 27682863, 2016). "In addition, CXCL1 was described to be secreted to promote immune cell recruitment and to alter the immune milieu in liver cancer." (PMID 36975480, 2023). "We also propose that CXCL8 and CXCL1 may be a potential therapeutic target for liver cancer treatment." (PMID 32730361, 2020). "CXCL8 or CXCL1 may offer effective approaches for the development of targeted molecular therapeutics for liver cancer." (PMID 32730361, 2020). "Moreover, CXCL8 or CXCL1 inhibition warrants further investigation as a candidate therapeutic target in liver cancer." (PMID 32730361, 2020). "Subsequently, CXCL1 and IL8 promote neutrophil recruitment and enhance the filtration of TAM in the liver, thereby facilitating liver cancer progression." (PMID 40342932, 2025). "By analyzing their relationship with the prognosis of liver cancer, we found the highly expressed CXCL8 and CXCL1 are related to the prognosis of liver cancer." (PMID 32730361, 2020). "In liver cancer cells, the aspartate kinase‐chorismate mutase‐tyrA prephenate dehydrogenase (ACT) domain of PHGDH binds nuclear cMyc to form a transactivation axis, PHGDH/p300/cMyc/AF9, which drives chemokine CXCL1 and IL8 gene expression." (PMID 37078828, 2023). "Studies have demonstrated that in liver cancer cells, the aspartate kinase-chorismate mutase-tyrosine aminotransferase (ACT) domain of PHGDH binds to nuclear cMyc, forming a transactivation axis involving PHGDH, p300, cMyc, and AF9, which drives the gene expression of chemokines CXCL1 and IL8." (PMID 40342932, 2025).
liver fibrosis (15 papers, 2012 to 2025). "Previous studies have shown that inhibiting glycolysis, specifically in endothelial cells (ECs), can lower CXCL1 production and is closely linked to the infiltration of neutrophils in liver fibrosis." (PMID 38943679, 2024). "Reduced levels of CXCL1 have been associated with advanced stages of hepatic fibrosis in adults with chronic hepatitis C virus infection." (PMID 30740106, 2019). "CXCL1 can also cause liver fibrosis through another pathway." (PMID 37408240, 2023). "CXCL1 acts on hepatic stellate cells, which causes an increase in α smooth muscle actin (αSMA) and α1(I) collagen expression in these cells, leading to liver fibrosis." (PMID 37408240, 2023). "IL-1α deficiency can reduce the risk of liver fibrosis in NASH by reducing the level of CXCL1." (PMID 34853322, 2021). "CXCL1 can activate HSCs through autocrine mechanisms, thereby contributing to the progression of hepatic fibrosis." (PMID 40421012, 2025). "Conversely, inhibition of glycolytic processes in LSECs impedes the production of CXCL1 and neutrophil infiltration, thus ameliorating the progression of liver fibrosis." (PMID 38943679, 2024). "For this reason, CXCL1 expression in the liver is positively correlated with liver fibrosis, for example, in patients with HCV infection." (PMID 37408240, 2023). "Current research on EVs focuses on three aspects: firstly, diseases are treated with EVs, for example, miR-150-5p in EVs from ADMSCs (ADMSC-EVs) relieves liver fibrosis by inhibiting the CXCL1 expression." (PMID 34348793, 2021). "In mice with CCL4-induced liver fibrosis, up-regulated CXCL1 expression in hepatic stellate cells has been reported to promote it activation and modulate liver fibrogenesis." (PMID 34395462, 2021). "Astonishingly, these findings are in line with seminal reports demonstrating that CXCL1, CXCL11, HIF1A, COL4A1, and FN1 are implicated in liver fibrosis." (PMID 32161843, 2020). "In summary, we demonstrate that CD147 promotes the CXCL1 expression in HSCs and modulates liver fibrosis." (PMID 29642635, 2018). "First, blockade of CXCL1, a critical chemokine to attract neutrophils, via the disruption of the Cxcl1 gene or treatment with a neutralizing anti-CXCL1 antibody, reduced hepatic neutrophil infiltration and liver fibrosis." (PMID 29552626, 2018). "In summary, we demonstrate that CD147 promotes the CXCL1 expression and modulates the liver fibrosis." (PMID 29642635, 2018). "In line with this, HSCs-specific CD147-knockout mice have greatly reduced HSCs activation and CXCL1 expression, leading to attenuated liver fibrosis." (PMID 29642635, 2018). "Taken together, these findings support our conclusions that CD147 stimulates the release of chemokine CXCL1 and promotes the development and progression of liver fibrosis." (PMID 29642635, 2018). "Consequently, inhibiting CXCL1 release induced by LSEC glycolysis is paramount for intervening in liver fibrosis." (PMID 38943679, 2024). "Therefore, further investigations are required to determine if QE can alleviate liver fibrosis by reducing CXCL1 production by inhibiting EC glycolysis and limiting neutrophil infiltration." (PMID 38943679, 2024). "To test whether neutrophils also contribute to the liver fibrosis in this model, we used 2 approaches to attenuate neutrophil infiltration via the inhibition of CXCL1 or ICAM-1, 2 important mediators for neutrophil infiltration." (PMID 29552626, 2018). "Blockade of CXCL1 with a neutralizing antibody or genetic disruption of the Cxcl1 gene markedly attenuated liver fibrosis in the HFD+1B ethanol-fed mice relative to IgG-treated or WT controls, as shown by the reduced Sirius Red–positive area and fibrosis-related gene expression." (PMID 29552626, 2018).
liver fibrosis (continued). "In a mouse model of liver fibrosis caused by CCl4, the expression of C-X-C-motif chemokine ligand 1 (CXCL1) was decreased when adipose MSC-Exos (AdiMSC-Exos) containing miR–150–5p were used, leading to improved liver fibrosis." (PMID 41244150, 2025). "CXCL1 has been shown to drive HSC activation and liver fibrosis." (PMID 34853322, 2021).
non-small cell lung carcinoma (15 papers, 2013 to 2025). A group of at least three distinct histological types of lung cancer, including non-small cell squamous cell carcinoma, adenocarcinoma, and large cell carcinoma. "CXCL1 has been mechanistically linked to tumorigenesis and metastatic progression across multiple malignancies, with well-documented roles in non-small cell lung carcinoma, mammary neoplasia, pancreatic adenocarcinoma, and cutaneous melanoma pathogenesis." (PMID 40176796, 2025). "The study on malignant pleural effusion in patients with non-small cell lung cancer has shown that CXCL1 is responsible for the recruitment of Treg cells." (PMID 37686093, 2023). "Non-small cell lung cancer (NSCLC) biopsy specimens have high intratumoral concentrations of CXCR2 ligands (CXCL1, CXCL5, and CXCL8) and type 2 cytokines interleukin-4 (IL-4), IL-5, IL-10, and IL-13." (PMID 23665907, 2013). "CXCL1 (Groα) gene encodes a secreted interleukine-like molecule binding specifically to G-protein-coupled receptor CXCR2 and potentially plays role in tumor-associated angiogenesis in non-small cell lung cancer." (PMID 26208990, 2015). "In terms of mechanism, IGFBP2/ITGA5 enhances the expression of CXCL1 by activating STAT3, thereby promoting gefitinib resistance in non-small cell lung cancer." (PMID 38918360, 2024). "The relationship between CXCL1 and DACH1 in non-small cell lung cancer (SCLC) deserves further investigation." (PMID 31998654, 2019). "It has also been reported that IL-17 augments the secretion of an array of angiogenic CXC chemokines, including CXCL1, CXCL5, CXCL6, and CXCL8 by three different non-small cell lung cancer cell lines." (PMID 23665907, 2013).
Hypertension (14 papers, 2017 to 2025). The presence of chronic increased pressure in the systemic arterial system. "Blockade of CXCL1/CXCR2 signaling attenuated KLF15 deficiency-induced accelerated cardiac remodeling, which provides a new KLF15/CXCL1 axis in regulation of hypertension-associated cardiac remodeling." (PMID 33869197, 2021). "Therefore, therapeutic targeting of the KLF15 or CXCL1/CXCR2 axis may serve as an innovative approach for the treatment of hypertension-associated cardiovascular disease." (PMID 33869197, 2021). "Four proteins (CXCL1, CD84, HO1, and PGF) were linked to disorders of blood pressure, including (early-onset) hypertension." (PMID 38958674, 2024). "Studies on mice have shown that angiotensin II-induced hypertension increases CXCL1/KC expression in the retina, which increases infiltration of the retina by CXCR2+ immune cells, particularly by neutrophils and macrophages." (PMID 36613652, 2022). "In mice treated with angiotensin II, the resulting hypertension is dependent on the CXCL1/KC→CXCR2 axis." (PMID 36613652, 2022). "Consistent with our data on RASMCs subjected to CMS, these data indicated that the expression of CXCL1 in SMCs is induced early in the course of hypertension." (PMID 29170451, 2017). "The expression of Cxcl1 was also induced in VSMCs by hypertension produced by abdominal aortic constriction (AAC)." (PMID 29170451, 2017). "The association of CXCL1 increase to the inflammatory activation of rat vascular SMC induced by hypertension, to the causes of hypertension and MMP9 release in human diseases, and to AAA growth support the potential relevance of Lad effects over CXCL1 in the perspective of AAA therapy." (PMID 41227357, 2025). "People with hypertension have higher levels of CXCL1 in their blood than healthy individuals." (PMID 36613652, 2022). "The blockage of CXCR2, the receptor of CXCL1, could suppress hypertension and end-organ damage in SHR and other hypertensive animal models." (PMID 33532132, 2021). "In this study, CXCL1 increased more obviously than CX3CL1 in RASMCs subjected to CMS, whereas Cxcl1, but not Cx3cl1, was increased in hypertension in vivo, suggesting that CMS in vitro mimics hypertension in vivo with regard to the expression of CXCL1 and CX3CL1." (PMID 29170451, 2017). "Taken together, these results indicate that CMS of VSMCs induces inflammation-related gene expression, including that of CXCL1 and CX3CL1, which may play important roles in the stress response against CMS caused by hypertension." (PMID 29170451, 2017). "Several studies suggest that CXC chemokines, such as CXCL1, and their receptor CXCR2 are strongly associated with the migration and recruitment of monocytes/macrophages and neutrophils in different inflammatory diseases, including hypertension, cardiac remodelling, and atrial fibrillation." (PMID 35981418, 2022). "To determine whether CXCL1 and CXCR2 are associated with HR in humans, we examined serum CXCL1 levels and the number of CXCR2+ immune cells as well as other related risk factors in healthy controls (n = 40) and patients with HR (n = 40) and hypertension (HP, n = 40)." (PMID 35981418, 2022). "In conclusion, our study identifies that KLF15 in cardiac fibroblasts negatively regulates CXCL1/CXCR2 axis-mediated inflammatory response and subsequent cardiac remodeling in hypertension." (PMID 33869197, 2021). "Recently, it has been reported that the CXCL1/CXCR2 axis is essential for recruitment of monocytes and macrophages into hearts and arteries in hypertension." (PMID 33869197, 2021). "In this study, we showed that CMS induces two chemokines, CXCL1 and CX3CL1, in a JNK-dependent manner and that CXCL1 is induced in hypertension by AAC." (PMID 29170451, 2017). "To further validate these data, we used an abdominal aortic constriction (AAC) mouse model to examine whether Cxcl1, Cx3cl1, and iNOS expression were induced by AAC-related hypertension in vivo." (PMID 38473793, 2024).